GFAP (glial fibrillary acidic protein)
Diseases named in the same sentence as GFAP in open-access papers (continued):
Sharing a sentence is not in itself a finding about the gene and the disease.
epilepsy (continued). "In epileptic specimens in post‐SE models of epilepsy, astrocytes adopt a “reactive” phenotype in which they become hypertrophic with long, thick processes and increased GFAP immunoreactivity." (PMID 35938285, 2025). "Numerous studies have shown that GFAP expression significantly increases after the onset of epilepsy." (PMID 40170730, 2025). "Astrocyte morphological changes in human hippocampal sclerosis specimens and in rodent models of epilepsy have largely been defined with GFAP immunoreactivity." (PMID 35938285, 2025). "fTSC2 KO mice with higher seizure numbers had IBA1 and GFAP expression in the range of control mice, suggesting that mice with more severe epilepsy had less inflammation compared to those with fewer seizures per day." (PMID 41255962, 2025). "Glial fibrillary acidic protein (GFAP) is regarded as a key marker of astrocyte response and proliferation following the onset of epilepsy and plays a critical role in the pathogenesis of the disorder." (PMID 40170730, 2025). "In experimental animals, pilocarpine-induced epilepsy results in a significant decrease in Kir4.1 expression, concomitant with a marked increase in GFAP in the hippocampus." (PMID 40170730, 2025). "An increase in GFAP levels is observed in epilepsy and other neurological diseases in reactive astrocytes and astrogliosis and is detrimental to their participation in maintaining ion homeostasis." (PMID 40507093, 2025). "It is widely recognized that increased GFAP expression in the context of epilepsy signifies astrocyte activation." (PMID 39006838, 2024). "Astrocytes in animal models of epilepsy can be abruptly activated by morphological and functional changes, leading to an increase in GFAP expression." (PMID 39598325, 2024). "There was a higher expression of GFAP in the amygdala of patients with epilepsy lasting for more than 20 years compared to those with epilepsy duration of less than 20 years (P ≤ 0.05)." (PMID 37658249, 2024). "The expression of the remaining four genes was upregulated in both datasets, with two of them (GFAP and S100A4) previously reported to be associated with epilepsy." (PMID 38212777, 2024). "For example, in an epilepsy model, Dex administration has been found to improve inflammation, prevent astrogliosis (based on GFAP and S100β expression), and partially reduce astroglial dysfunction." (PMID 39036088, 2024). "In the present work we investigated, during the different phases of epilepsy, in the rat hippocampus, the regulation of the neuroinflammatory GFAP and Iba1 markers and vascular proteins of the BBB, such as CD31, PDGFRβ, and ColIV." (PMID 38338969, 2024). "To explore the effect of YTHDC2 knockdown on epileptic seizures, we injected an AAV carrying the GFAP promoter and eGFP into the bilateral hippocampus of mice with epilepsy to specifically reduce YTHDC2 expression in astrocytes." (PMID 39310099, 2024). "Regarding studies on epilepsy in humans, a transient but marked increase in GFAP was evidenced immediately after (2 h) a single tonic–clonic (TC) seizure." (PMID 37569895, 2023). "This contrasts with previous reports on the up-regulation of GFAP induction in the hippocampal kindling model and protein level increase in the pilocarpine model of epilepsy in rats." (PMID 36362260, 2022). "Astrogliosis, which refers to an abnormal increase in astrocytes, usually occurs when an insult to the brain is sustained and often presents in patients with tuberous sclerosis syndrome or epilepsy; elevated GFAP expression is a marker of astrogliosis." (PMID 33957945, 2021). "Seventy-two hours after SE, a high increase of GFAP-positive cells was noted, which can be explained by the fact that, in animal models of epilepsy, astrocytes are rapidly activated with the hypertrophy of cell bodies, thus increasing the expression of GFAP." (PMID 33810180, 2021). "Hippocampal slices were stained with antibodies directed against NeuN, GFAP, and Hoechst 4 weeks after epilepsy induction." (PMID 34025561, 2021).
epilepsy (continued). "Our findings harmonize with previous studies that revealed a rapid amplified GFAP expression in various animal models of epilepsy, including PTZ, electrical kindling, and kainic acid." (PMID 34690772, 2021). "After miR-103a inhibitors interfered with epilepsy rats, there showed decreased expression of miR-103a and GFAP, increased expression of BDNF and decreased number of apoptotic neuron as well as increased number of surviving neurons." (PMID 31049031, 2019). "Previously, the only other work that has studied GFAP-immunoreactivity in marmosets was in animals with chemically induced epilepsy." (PMID 30678038, 2019). "In experimental animal models of epilepsy, astrocytes are rapidly activated with the hypertrophy of cell bodies, thus increasing the expression of GFAP." (PMID 31022879, 2019). "Nestin cells represented 29% of the hippocampal proliferative fraction in epilepsy cases; 20% co‐expressed βIII tubulin in culture compared with 28% with GFAP." (PMID 28925561, 2018). "The increment in GFAP, induced in the Li-pilocarpine model of epilepsy, was prevented by dexamethasone in animals at 1 and 56 days after pilocarpine injection (p = 0.0035 and p = 0.0245, respectively)." (PMID 29506554, 2018). "We suggested in our previous studies that UR lowers KA-induced lipid peroxide levels and offers neuroprotection against KA-induced epilepsy by regulating GFAP and S100B." (PMID 28386293, 2017). "PAX6/GFAP double‐labeled cells were numerous in the superficial cortex, white matter, and deeper cortex in all epilepsy cases." (PMID 27231702, 2016). "In epileptic animal models with long-term epilepsy, GFAP immunoreactivity increased with the seizure process." (PMID 21837247, 2012). "In line with the gene expression results, enhanced GFAP protein expression has been detected within days after SE in the hippocampus of various experimental epilepsy models in the immature (P15–P21), and adult rats." (PMID 20505763, 2010). "Primary astrocytes were isolated and cultured from seven epilepsy brain resections and astrocyte purity was defined by GFAP reactivity." (PMID 17535102, 2007). "GFAP is a specific marker for astrocytes, which may play a key role in epilepsy because of their impaired or dysfunctional function." (PMID 40217560, 2025). "Multiple plasma proteins have been suggested to be epilepsy biomarkers, but many are neuronal proteins associated with non-specific brain injury (tau, GFAP, UCHL1, etc.)." (PMID 39812831, 2025). "Mitotic labeling with Ki‐67 and double‐labeling with GFAP and/or with fluorescent astrocytes would possibly enable the determination of the degree of de novo astrocyte proliferation at various time points during epileptogenesis in rodent models of epilepsy." (PMID 35938285, 2025). "Blood neurofilament light, glial fibrillary acidic protein, total tau, S100 calcium-binding protein B and neuron-specific enolase concentrations were measured in 444 patients (aged ≥ 18 years) with epilepsy participating in a prospective regional Biobank study in Västra Götaland (Sweden)." (PMID 40114782, 2025). "Recently published research demonstrated that active epilepsy in individuals with TSC is associated with elevated levels of GFAP compared to those with TSC but without epilepsy." (PMID 41341265, 2025). "Increased levels of GFAP are observed in epilepsy and are indicative of astrogliosis." (PMID 40015967, 2025). "Similarly, in only 3 of 29 patients with epilepsy, the peripheral GFAP level was shown to be increased after status epilepticus." (PMID 33377994, 2021). "Although hippocampi of many epilepsy patients demonstrate DG and/or hilus infiltration by GFAP+ astrocytes indicative of injury-driven gliosis, this alteration was absent in 1 of the 4 seizure-affected hippocampi and in all 4 control brain samples with GCD that we tested." (PMID 32317027, 2020).
epilepsy (continued). "Our study also demonstrated that inhibiting miR-103a expression can inhibit the activation of astrocytes in epilepsy rats, which is reflected by the results that the mRNA and protein expression of GFAP were significantly lower in the EP + miR-103a inhibitors group." (PMID 31049031, 2019). "Compared with miR-103a inhibitors alone, epilepsy rats treated with BDNF-siRNA combined with miR-103a inhibitors significantly increased expression of GFAP in hippocampal tissues of epilepsy rats, increased number of apoptotic neurons and significantly decreased the number of surviving neurons." (PMID 31049031, 2019). "In particular, astrogliosis is especially common in epilepsy and is characterized by morphological and functional changes in astrocytes, including hypertrophy of primary processes, variable upregulation of glial fibrillary acidic protein (GFAP), and in some cases, increased astrocyte proliferation." (PMID 28588256, 2017). "Ward’s unsupervised cluster analyses based on the “global epilepsy” score also allowed us to investigate whether individuals with larger deletions and consequently with higher GFAP scores and worse prognosis are more likely to exhibit a severe or pharmaco-resistant epilepsy." (PMID 41303083, 2025). "Serum glial fibrillary acidic protein (GFAP), detectable with ultrasensitive assays such as Simoa, serves as a marker of astrocytic injury that correlates with disease severity and seizure burden, though it lacks specificity to epilepsy as it elevates in various neurodegenerative conditions." (PMID 41458814, 2025). "Furthermore, an increase in GFAP‐stained cytoskeleton may even develop in parallel with atrophy of peripheral astrocytic processes as has been demonstrated in experimental epilepsy." (PMID 33675569, 2021). "As neuronal loss and gliosis are the two main characteristics of hippocampal sclerosis in epilepsy, in order to evaluate the effect of pilocarpine-induced SE on the hippocampal neurons and astrocytes in our study, immunofluorescence was carried out against both NeuN and GFAP." (PMID 33192357, 2020). "We explored blood levels of NfL, GFAP, total tau, S100B and NSE in a regional epilepsy cohort, with a focus on DRE." (PMID 40114782, 2025). "The expression of GFAP in epileptic rats and TLE patients was determined by immunofluorescence to elucidate the astrocyte reaction involved in epilepsy." (PMID 33134289, 2020). "Increased expression of miR-103a, GFAP, and number of apoptotic neurons, decreased expression of BDNF and number of surviving neurons were found in hippocampus tissues of epilepsy rats." (PMID 31049031, 2019). "Unlike NfL, the increased levels of GFAP seen in our cohort seem to reflect structural pathology rather than the seizures or chronic state of epilepsy in individuals with DRE." (PMID 40114782, 2025). "To ensure that the differences seen for NfL and GFAP did not reflect structural abnormalities related to the epilepsy, we excluded participants with lesions." (PMID 40114782, 2025). "Primary outcome measures included epilepsy latency, Morris water maze escape latency, oxidative stress markers (MDA, GSH, SOD), inflammatory factors (IL-1β, TNF-α), and Glial fibrillary acidic protein (GFAP)." (PMID 40709096, 2025). "In the amygdala, multiple regression analyses showed that the expression of GluR2 and Cav2.1, as well as GFAP and EAAT1, could best predict the total number of seizures and epilepsy duration, respectively." (PMID 37658249, 2024). "In effect, the populations and areas of IBA-1 + and GFAP + cells were significantly increased in CA1 and CA3 areas in epileptic hippocampus, indicating the activation of microglia and astrocytes after KA induction of epilepsy." (PMID 38087170, 2024).
epilepsy (continued). "Our recent study confirmed that TRPV4 and glial fibrillary acidic protein (GFAP) are synchronously upregulated in human hippocampal tissues from TLE patients and a 4-aminopyridine (4-AP)-induced epilepsy mice, and also explored the functional activity of TRPV4 promotes the reactivity of astrocytes." (PMID 37880726, 2023). "Taken together with Western blot data, this result suggests that there are no changes in GFAP expression or distribution as in human epilepsy or other animal models." (PMID 36362260, 2022). "Our preclinical studies and other clinical studies imply that GFAP is not a reliable peripheral marker in epilepsy." (PMID 33377994, 2021). "To this extent, we used surgically resected brain tissue from patients with drug‐resistant epilepsy due to FCD IIb or TSC and a mouse epilepsy model based on conditional Tsc1 deletion in glial fibrillary acidic protein (GFAP) expressing cells (Tsc1GFAP−/− mice) to investigate these interactions." (PMID 31869431, 2020). "We observed increased gliosis in some of the cadaveric seizure-affected hippocampi, independent of GCD, although the DG in every epilepsy case did not have increased GFAP+ astrocytes." (PMID 32317027, 2020). "The only other postmortem immunohistochemical studies of human VIM-IR astrocytes have confirmed their presence in the brainstem, where, unlike GFAP-IR astrocytes, they have a reduced density in sudden unexpected death in epilepsy." (PMID 32848635, 2020). "In no epilepsy cases, with CV, synaptophysin, or GFAP did we identify distinct atrophy or sclerosis of a nucleus comparable to the degree of hippocampal damage in CHS." (PMID 24138281, 2013). "mPGES (membrane-bound PGE2 synthase) increases production of glial fibrillary acidic protein (GFAP)-positive astrocytes following seizure kindling, whereas PGE2 antagonists reduce seizure severity and seizure-induced neurological damage in experimental epilepsy." (PMID 29764485, 2018). "Chronic neurological conditions (e.g., migraines and epilepsy), however, do not appear to influence GFAP levels to a degree that would be expected to confound the usefulness of GFAP as a TBI biomarker (although there are few studies relating to chronic conditions)." (PMID 29255443, 2017). "Furthermore, evidence suggests that GS reactivity increases during the latent phase of epilepsy and that in patients with advanced temporal lobe epilepsy (TLE), the loss of GS+ astrocytes, rather than changes in GFAP+ astrocytes, correlates with neuronal degeneration." (PMID 41008549, 2025). "In the epilepsy rat model, double-label immunofluorescence staining showed that Npas4 and MAP2 were co-expressed in neurons in the cortex and hippocampus but were not co-expressed with GFAP, an astrocyte marker, in neuroglia cells in the hippocampus and cortex." (PMID 25536221, 2014).
Anxiety (84 papers, 2007 to 2026). Intense feelings of nervousness, tension, or panic often arise in response to interpersonal stresses. "Elevated GFAP was associated with acute onset, atypical presentation, infectious prodrome, tics, depressive/anxiety symptom ratings and overall greater psychiatric symptom burden." (PMID 39048548, 2024). "They found significant anxiety-like behaviors 1 week following a single bTBI that was associated with elevated levels of GFAP and IBA-1 within the amygdala." (PMID 32760340, 2020). "A recent study indicated that an infusion of inflammatory cytokine in the hypothalamus’ paraventricular nucleus (PVN) increased GFAP expression with associated enhanced anxiety-like behaviors." (PMID 31863052, 2019). "In addition, linear regression analyses revealed that blood SII, AISI, and serum GFAP levels were significantly associated with anxiety in H. pylori-positive patients." (PMID 41210138, 2025). "Interestingly, elevated GFAP levels were also associated with increased levels of anxiety and the occurrence of tics, which are symptom criteria for Paediatric Acute-onset Neuropsychiatric Syndrome (PANS)." (PMID 39048548, 2024). "This augmented pain phenotype was significantly associated with increased glial fibrillary acidic protein immunofluorescence in pain-associated brain regions, identifying supraspinal astrocyte activation as a significant mechanism underlying anxiety-augmented pain behaviour." (PMID 30779717, 2019). "Overall, these data show that the ‘downstream’ RASopathy-linked Raf1L613V mutation increases the number of GFAP+ astrocytes and OPCs and improves aspects of learning and memory without significant alterations in basal behavioral measures of anxiety or sociability." (PMID 31017896, 2019). "Initial behavioral analyses indicate that neurogenesis-deficient GFAP-TK rats are similar to neurogenesis-intact wild-type littermates in general locomotion and baseline anxiety but display reduced sucrose preference, suggesting alterations in reward-related behaviors." (PMID 27257630, 2016). "Therefore, GFAP-associated astrocyte activation as a critical link may connect systemic inflammation with anxiety development in patients with H. pylori infection." (PMID 41210138, 2025). "To explore the role of astrocytes in modulating CRS-induced anxiety-like behaviors, we performed staining for glial fibrillary acidic protein (GFAP), an astrocyte marker, to assess for astrocyte activation." (PMID 40777598, 2025). "In this study, we found that EA intervention increased the PWTs, prevented anxiety-like behaviors related to inflammatory pain, enhanced PV expression, and decreased GFAP expression in the ACC." (PMID 40890793, 2025). "In the light/dark box task, anxiety-like behaviors decreased in both Syn1 KI and GFAP KI mice treated with ACTH." (PMID 40015967, 2025). "Mood disorder: Brain GFAP expression was quantified in 9 of 13 studies addressing the MGA axis in anxiety and depressive-like behaviour (ELISA, IF, IHC, or WB)." (PMID 40485663, 2025). "Subsequent mediation analyses further revealed that serum GFAP potentially affected the relationship between systemic inflammatory markers and anxiety severity in these patients." (PMID 41210138, 2025). "Further mediation analyses in H. pylori-positive patients demonstrated that serum GFAP significantly mediated the relationship between systemic inflammation indices and anxiety severity." (PMID 41210138, 2025). "Mice would develop in anxiety and consequently increase the GFAP density when experiencing long‐term NP." (PMID 39838823, 2025). "The combination of MS (P2–14) and LPS (P3) induced a synergistic effect on the anxiety-like behaviour, locomotor activity, and GFAP mRNA expression outcomes that were investigated in this manuscript." (PMID 38397434, 2024).